IL10 (interleukin 10)
Diseases named in the same sentence as IL10 in open-access papers (continued):
Sharing a sentence is not in itself a finding about the gene and the disease.
atopic dermatitis (continued). "Moreover, the expression level of the interleukin-10 (IL-10) mRNA, a characteristic feature of atopic dermatitis, was significantly suppressed following the ItP of IL-10 siRNA." (PMID 38140019, 2023). "Here, we also pooled the available data to perform a meta-analysis, which did not strongly support the genetic relationship between the IL-10 -592 C/A SNP and the risk of atopic dermatitis." (PMID 31101031, 2019). "A negative association between the IL-10 -819 T/C polymorphism and atopic dermatitis risk was also reported in Saudi Arabia and Taiwan of China." (PMID 31101031, 2019). "The current evidence does not support a strong genetic relationship between IL-10 -1082 A/G, − 819 T/C and − 592 A/C polymorphisms and the susceptibility to atopic dermatitis." (PMID 31101031, 2019). "Atopic dermatitis decreased the expression of IL-10 in BALB/c mouse in an SOCS1-dependent manner." (PMID 30459600, 2018). "IL-10 repressed the expression of anti-microbial peptide in atopic dermatitis." (PMID 28978148, 2017). "Because VV has a proclivity for replicating/disseminating in inflamed skin (e. g. in individuals with atopic dermatitis), IL-10 could also influence VV replication by reducing VV-induced inflammation." (PMID 26991092, 2016). "Overall, based on the current case-control association data, IL-10 -1082 A/G, − 819 T/C and − 592 A/C polymorphisms may not be strongly related to atopic dermatitis susceptibility, which would be greatly strengthened by a larger sample size." (PMID 31101031, 2019). "Our findings suggested that the IL-10 -819 T/C SNP may not be associated with the risk of atopic dermatitis." (PMID 31101031, 2019). "Network analysis of the proteins encoded by the upregulated transcripts showed significant enrichment for IL‐10 signalling (Reactome pathway FDR 7.71e‐08) which plays a suppressive role in contact dermatitis and atopic eczema." (PMID 40462597, 2025). "Patients with atopic dermatitis seem to have a higher expression of TGF-β and other inflammatory cytokines like IL-6, IL-8 and IL-10 compared to healthy individuals." (PMID 34012511, 2021). "We found that IL-10 -819 T/C SNP may not be strongly linked to the risk of atopic dermatitis." (PMID 31101031, 2019). "In summary, the IL-10 -1082 A/G SNP may have no genetic effect on the risk of atopic dermatitis." (PMID 31101031, 2019). "Marked decrease in plasma IL-10 levels accompanies marked increase in RANTES levels in patients with severe, treatment-resistant atopic dermatitis." (PMID 23566546, 2013). "In atopic dermatitis, a marked increase in plasma RANTES levels accompanied by a marked decrease in IL-10 levels is observed." (PMID 23566546, 2013). "This genus has been found to be reduced in children with food allergy or sensitization or with AR and in adult-onset atopic dermatitis (AOAD) while Fusicatenibacter has anti-inflammatory properties, inducing IL-10 in intestinal mucosa to exert anti-inflammatory effects." (PMID 39683566, 2024). "(2014) reported a significant increase in IL‐4 concentrations in dogs with atopic dermatitis, while no change in IL‐6 and IL‐10." (PMID 38648253, 2024). "In human clinical trials, intramuscular administration of autologous total IgG significantly increased the percentage of IL-10-producing CD4+ Treg cells in the peripheral blood of healthy subjects and provided significant clinical improvements in patients with atopic dermatitis." (PMID 38094290, 2023). "The difference in the baseline functional states of regulatory T cells might result in discrepancy of changes in serum IL-10 and IFN-γ levels between patients with atopic dermatitis and healthy human subjects." (PMID 35665739, 2022). "Suppression of Th1 cells by Th2 cells seems to be abrogated by decreased IL-10 and Th2 cytokines, which may be mediated through elevated RANTES in patients with severe atopic dermatitis." (PMID 23566546, 2013).
atopic dermatitis (continued). "Maternal inflammatory cytokines (MCP‐1, IL‐10, TNF‐α) in late pregnancy have been shown to correlate with offspring's levels of the same cytokines in cord blood and at age 1 year but not with the offspring's risk of atopic eczema." (PMID 40714954, 2025). "Sleep disturbances in atopic dermatitis are not only due to sleep deprivation related to nighttime itching but also to dysregulation in the release of inflammatory mediators (IL-1b, IL-2, TNF-a, IFN-g, IL-6, IL-4, and IL-10) and neuroendocrine molecules such as cortisol and melatonin." (PMID 38731996, 2024). "In our previous studies, we showed that intramuscular administration of autologous total IgG could induce significant clinical improvements and increases of the serum levels of interleukin-10 (IL-10) and interferon-gamma (IFN-γ) in patients with atopic dermatitis." (PMID 35665739, 2022). "However, we cannot exclude a possibility that the dose and duration of intramuscular administration of autologous total IgG required to increase serum IL-10 and IFN-γ levels in healthy human subjects are higher and longer compared to patients with atopic dermatitis." (PMID 35665739, 2022).
myeloma (60 papers, 2008 to 2025). "IL-10 is an inflammatory cytokine that is primarily produced by myeloma-associated macrophages and plays a key role in B cell proliferation and plasma cell differentiation." (PMID 37937298, 2023). "IPA analysis revealed B Cell Receptor Signaling (p = 1.90E−03), RhoGDI Signaling (p = 1.22E−03), and IL-10 Signaling (p = 1.43E−03) as the top canonical pathways associated with 17-AAG sensitivity in myeloma based on the genes that were DE." (PMID 35264575, 2022). "Treg have been implicated in myeloma progression based on their contribution to the complex immunosuppressive environment through secretion of cytokines IL-10 and TGF-β, as well as direct inhibition of effector T cell responses." (PMID 31428081, 2019). "Bregs are associated with immunosuppression in myeloma and less Bregs could suppress IL-10 expression, thus limiting Treg expansion." (PMID 38111533, 2023). "IL-1β, IL-6, TNF-α, and IL-10 may cause osteopenia, IL-6 and IL-10 gammopathies and lead to multiple myeloma." (PMID 30781349, 2019). "The role of IL-10 within the tumor milieu remains uncertain; nonetheless, studies indicate that both VEGF and IL-10 levels are elevated in multiple myeloma relative to healthy individuals and rise concurrently with the ISS stage." (PMID 40647640, 2025). "Meanwhile, IL-10, a potent immunosuppressive cytokine, supports tumor progression by enhancing myeloma cell survival, dampening anti-tumor immune responses, and promoting resistance to therapy." (PMID 40002248, 2025). "Previous studies highlighted a significant correlation between IL-10 and the percentage of plasma cells in multiple myeloma patients as it induces the proliferation of plasma cells (Refs 117–119)." (PMID 38186186, 2024). "IL-10+ Bregs have also been found to promote the suppressive effect of MDSCs and abrogate NK cell-mediated lysis of tumour cells in cancers such as Multiple Myeloma." (PMID 39346706, 2024). "Pooled HSPs, including gp96 from established murine myeloma cell lines, showed promise as an off-the-shelf vaccine effectively treating mice with large myeloma tumor burdens with HSP combined with anti-B7H1 or anti–IL-10 monoclonal antibodies." (PMID 39161773, 2024). "Despite its purported role as a growth factor in myeloma, the role of IL-10 in MM remains to be elucidated." (PMID 37250588, 2023). "That is why we performed this work to evaluate the prognostic role of RDW%, NLR and IL-10 in Egyptian multiple myeloma patients." (PMID 37937298, 2023). "The authors confirmed the ability of S100A9 to induce the secretion by myeloid-derived suppressor cell (MDSCs) of inflammatory and pro-myeloma cytokines including TNFα, IL-6, and IL-10." (PMID 34445745, 2021). "The immune suppressive myeloma microenvironment has elevated IL-10 and TGF-beta, and was associated with decreased expression of NK activating receptors, TNF and IFN-γ secretion, and impaired NK cytotoxicity toward myeloma." (PMID 33746969, 2021). "Otherwise, CD38 blocking with Isatuximab in Treg cells from Myeloma Multiple patients has demonstrated a reduced IL-10 expression and a higher amount of IFN-γ expression in CD8+ T-cells." (PMID 34769406, 2021). "APRIL and BCMA promote cell growth (via MAPK and NFκB) and immunosuppression (via PD-L1, TGF- ß, and IL10) in myeloma cells." (PMID 33634031, 2020). "For example, studies have shown that, in myeloma patients, CD19+CD24hiCD38hi Bregs can eliminate the toxic effect of NK cells on myeloma cells by secreting IL-10." (PMID 31662750, 2019). "DCs loaded with chaetocin-treated dying myeloma cells produced low levels of IL-10 and enhanced the cross presentation of DCs." (PMID 28512265, 2017). "Unraveling the mechanistic impact of IL-10 production in myeloma-reactive or cancer-reactive effector T cells has major relevance for optimizing immunotherapy." (PMID 28642819, 2017).
myeloma (continued). "In summary, we found that CCL27, a novel chemokine in the context of the bone marrow microenvironment, confers myeloma drug resistance to proteasome inhibitors by binding to stromal CCR10 and inducing IL-10, a myeloma survival factor." (PMID 27732933, 2016). "IL-10 is discussed as a survival factor for myeloma cells and is induced in myeloma-stroma coculture, which we also confirmed." (PMID 27732933, 2016). "IL-10 has been involved in the activation of myeloma cells, supporting their long term growth responding to IL-6." (PMID 23936794, 2013). "In contrast, IL-10 (immune suppressive cytokine) and IL-6 (enhancer of myeloma cell) expression was increased in MM patients." (PMID 23152910, 2012). "Our model system demonstrates, for the first time, a direct induction of TReg cells (tTReg cells) by both fresh myeloma cells and cell lines that demonstrate the phenotype and functionality of TReg cells whilst inducing IL-10 production in non TReg cells." (PMID 22666318, 2012). "In vitro assays demonstrated a critical role of Stat3, a key downstream component of IL-10 signaling, in the survival of human multiple myeloma cells." (PMID 22642622, 2012). "Gene expression profiling of B cells from M-protein-positive p80HT mice revealed aberrant expression of genes known to be important in the pathogenesis of multiple myeloma, including cyclin D1, cyclin D2, Blimp1, survivin, IL-10 and IL-15." (PMID 22642622, 2012). "For instance, interaction between myeloma cells and plasmacytoid DC in MM bone marrow (BM) triggers the release of known MM-cell growth factors, including IL-10, IL-6, and MCP-1 or IP10." (PMID 23232072, 2012). "The myeloma cell growth activity of IL–10 is mediated through a gp130 cytokine, oncostatin M (OSM) that is frequently produced by myeloma cells." (PMID 22567049, 2011). "It should be noted that almost one third of multiple myeloma patients had IL–6 pos.–174 GG genotype and 62% IL–10 GCC haplotype." (PMID 22567049, 2011). "In addition, TGF-β1 and IL-10 secreted by myeloma have a role in inhibiting CD80/CD86 upregulation during DC maturation." (PMID 38464531, 2024). "IL-1b, TNF-a, IL-6, and IL-10 may contribute to osteopenia; IL-1b, TNF-a, and IL-6 may have a role in the activation of coagulation and hypermetabolism; IL-6 and IL-10 may be responsible for gammopathies and multiple myeloma." (PMID 36498496, 2022). "IL-1b, TNF-a, IL-6, and IL-10 may contribute to osteopenia; IL-6 and IL-10 may be responsible for gammopathies and multiple myeloma; IL-1b, TNF-a, and IL-6 may have a role in the activation of hypermetabolism." (PMID 36498496, 2022). "IL-10, produced by T regulatory cells or myeloma cells, also contributes to the development of MM." (PMID 33923357, 2021). "Even fully mature plasma cell stages in the bone marrow retain the capability to produce IL-10 [936, 1063, 1213], and IL-10 production by malignant plasma cells may contribute to the immunodeficiency observed in multiple myeloma [1062]." (PMID 34910301, 2021). "Furthermore, following 01A treatment, APRIL-induced expression of genes involved in immunosuppression, i.e., PD-1, transforming growth factor beta (TGF-β), and interleukin 10 (IL-10), is decreased in multiple myeloma cells." (PMID 31548533, 2017). "Researchers also found that several human multiple myeloma cell lines could spontaneously produce IL-10 up to 179 pg/ml and their IL-10 production could raised up to 1626 pg/ml when they were stimulated by IL-6." (PMID 28234961, 2017). "In this study, we demonstrated that DCs loaded with chaetocin-treated dying myeloma cells were recovered by increasing the expression of maturation molecules and producing low levels of the inhibitory cytokine IL-10 compared with DCs loaded with UVB-irradiated dying myeloma cells." (PMID 28512265, 2017). "Moreover, we found that pretreatment of myeloma cells with chaetocin enhanced DCs functions through inhibiting the production of IL-10 and enhancing the cross presentation of DCs." (PMID 28512265, 2017).
myeloma (continued). "Following treatment with BI836909, selective lysis of BCMA-positive myeloma cells, activation and proliferation of T cells, as well as release of multiple key cytokines related to effector T cell function (IFNγ, IL-2, IL-6, TNFα, IL-10) were noted." (PMID 31548533, 2017). "Concomitantly, surface expression of monoclonal immunoglobulin was decreased on IL-10 treated myeloma cells (NCI-H929, IgA myeloma; OPM-2, IgG myeloma), whereas we found higher levels of free immunoglobulin in the supernatants of these cells upon CCL27 +/− bortezomib treatment." (PMID 27732933, 2016). "It is likely that microenvironmental IL-10 is immediately utilized by the myeloma cells and therefore efficient targeting might be hard to accomplish." (PMID 27732933, 2016). "From our data we suggest that blocking the CCR10/CCL27/IL-10 myeloma-stroma crosstalk is a novel therapeutic target that could be especially relevant in early refractory myeloma patients." (PMID 27732933, 2016). "Moreover, the concentrations of IL-10 in different clinical myeloma stages showed a positive correlation with disease progress." (PMID 23936794, 2013). "Additionally, a significant correlation was noted between BAFF and IL-6 serum levels, suggesting the important role of IL-10 in myeloma progression." (PMID 23936794, 2013). "64% of the multiple myeloma patients had IL–10 – GCC haplotype compare to the controls." (PMID 22567049, 2011). "The myeloma cell adheres to the bone marrow (BM) microenvironment, and thereby stimulates angiogenesis and enhances the stimulation of cytokines such as IL–1β, IL–6 and IL–10." (PMID 22567049, 2011). "The importance of cytokines (eg, interleukin IL-6, IL-1β, IL-10, and tumour necrosis factor-α) and the role of cross talk between myeloma cells and the bone marrow microenvironment in the proliferation, apoptosis and migration of myeloma cells and patient survival is becoming clearer." (PMID 18813242, 2008). "Other factors that drive T-cell anergy in the myeloma microenvironment are immunosuppressive cell subsets like regulatory T-cells (Tregs) and myeloid-derived suppressor cells (MDSCs), or cytokines like interleukin-10 (IL-10) and transforming growth factor-β (TGF-β)." (PMID 32659909, 2020). "This study focused on the role of IL-10 in MM cell line proliferation and resistance to anticancer drugs, considering that there are numerous reports on the role IL-6 in survival and proliferation of multiple myeloma (MM) cells through the phosphorylation of STAT3." (PMID 27418139, 2017). "The regulation and role of IL-10 produced from myeloma-reactive PD-1+ T cells is entirely unknown." (PMID 28642819, 2017). "Moreover, we correlated them with markers of myeloma activity, such as serum levels of IL-6, IL-10, IL-15, beta-2 microglobulin (B2M), and C-reactive protein (CRP), as well as with plasma cells' infiltration and Ki-67-PI in the bone marrow, both in diagnosis and after effective therapy." (PMID 23936794, 2013). "Regulatory B cells (Bregs) in the myeloma microenvironment facilitate immune tolerance by secreting transforming growth factor-β (TGF-β), interleukin-10 (IL-10), and interleukin-35 (IL-35), suppressing anti-tumor immune responses." (PMID 40002248, 2025). "S100A9 induced MDSC to express and secrete inflammatory and pro-multiple myeloma cytokines, including TNFα, IL6, and IL10." (PMID 36923707, 2023). "APRIL facilitates myeloma cell growth and survival and stimulates the upregulation of TGF-β and IL-10, thereby promoting the survival of Tregs via TACI signaling." (PMID 35886976, 2022). "When the cytokine production of MM-MSCs in response to the RPMI8226 myeloma cell line was examined in a 3D culture of gelatine sponge scaffolds, higher secretion of IL-11 and HGF and less IL-10 was observed as compared to 2D cultures." (PMID 34067236, 2021).